KMT2C (lysine methyltransferase 2C)
Diseases named in the same sentence as KMT2C in open-access papers (continued):
Sharing a sentence is not in itself a finding about the gene and the disease.
leukemia (24 papers, 2013 to 2025). A malignant (clonal) hematologic disorder, involving hematopoietic stem cells and characterized by the presence of primitive or atypical myeloid or lymphoid cells in the bone marrow and the blood. "As a tumor suppressor, KMT2C/MLL3 is linked to various cancers, including leukemia, breast, and bladder cancer." (PMID 41301465, 2025). "The loss of KMT2C in mice leads to aberrant myelopoiesis, causing myeloid infiltration into lymphoid organs; however, the loss of KMT2C alone is insufficient to drive leukemia." (PMID 38203823, 2024). "The MLL family is known as myeloid/lymphoid or mixed-spectrum leukemia proteins, and mutations, deletions and low expression of the gene KMT2C (MLL3) appear to play an important role in the development of leukemia." (PMID 39165358, 2024). "Inc.reased GALNT11 expression has been reported for leukemia, and KMT2C has been associated with tumorigenesis." (PMID 38137484, 2023). "These mutations have typically been seen in leukaemia and other blood malignancies but other more recent studies have demonstrated that these mutations occur amongst a wide variety of other cancers and are targetable by inhibitors of KMT2C function." (PMID 33632293, 2021). "KMT2C not only may act as a tumor suppressor in leukemias and T-cell lymphomas,75, 76but it is also implicated in bladder, breast, colorectal, endometrial, gastric, head and neck, lung, and liver cancer, and in medulloblastoma." (PMID 32939516, 2020). "KMT2C, also known as MLL3 in humans, is a tumor suppressor associated with leukemia and other solid tumors that has histone methylation activity for transcriptional synergistic activation." (PMID 35058979, 2022). "We next determined the effect of SNDX-5613 on in vivo leukemia-initiating potential of primary PD AML cells harboring MLL-AF9 plus FLT-3 N676T, as well as mutations in KMT2C, KMT2D, NOTCH2, IRF8, ARID1A, VPS13A, and ABCA7, which were determined by whole-exome sequencing." (PMID 35017466, 2022). "Interestingly, Kmt2c alterations were identified recurrently in all three leukemias." (PMID 40394211, 2025). "For example, missense and nonsense mutations targeting the mixed lineage leukemia family member 3 (MLL3, encoded by KMT2C) histone methyltransferase occur in a range of solid tumors, and heterozygous deletions encompassing KMT2C occur in a subset of aggressive leukemias." (PMID 37261974, 2023).
bladder cancer (22 papers, 2015 to 2025). "KMT2C plays a repressive role in bladder cancer and is one of the most commonly mutated genes in BCa patients." (PMID 39165358, 2024). "Additionally, the most frequently mutated genes in ordinary bladder cancer are KMT2C, ATM, FAT1, CREBBP, ERBB2, SPTAN1, and KMT2A." (PMID 39399176, 2024). "As was demonstrated for bladder cancer, tumor cells with low KMT2C activity experienced a deficiency of DNA repair mediated by homologous recombination and suffer from endogenous DNA damage and genomic instability, and their treatment with the PARP1/2 inhibitor olaparib leads to synthetic lethality." (PMID 34572812, 2021). "Furthermore, deficiency of the KMT2C protein in bladder cancer cells was found to be associated with the modified expression of genes involved in the DNA-damage response (DDR) and DNA repair." (PMID 33302406, 2020). "In region-common mutations, missense mutations of KMT2C encoding MLL3 were frequently observed (5 cases), suggesting that mutations on this epigenetic regulator might represent early genomic alterations in the development of bladder cancer." (PMID 33287735, 2020). "Bladder cancer cells with low KMT2C activity lack homologous recombination-mediated DNA repair of double-strand breaks, resulting in greater endogenous DNA damage, leading to genomic instability and promoting tumorigenesis." (PMID 39165358, 2024). "Although previous findings have shown that KMT2C is a promising target for the treatment of cervical and bladder cancers, the specific molecular mechanisms involved in the regulation of KMT2C in cervical and bladder cancers remain to be further investigated." (PMID 39165358, 2024). "Specifically, downregulation of KMT2C in bladder cancer cells results in widespread changes in epigenetic status and expression of DNA damage response and DNA repair genes." (PMID 39165358, 2024). "The most frequently mutated genes in ordinary bladder cancer are TP53x, KMT2A, SPTAN1, ERBB2, CREBBP, FAT1, ATM, and KMT2C." (PMID 36779496, 2023). "Previous studies have found that NCOR1 and KMT2C/D play oncogenic roles in bladder cancer, colorectal cancer, prostate cancer, and lymphomagenesis." (PMID 36072793, 2022). "Epigenetic state is altered in bladder cancer cells with low KMT2C activity, followed by the decreased expression of DNA damage/repair genes." (PMID 33159839, 2021). "We found that similarly to bladder cancer (BC), KMT2C is downregulated in comparison with normal tissue in colorectal adenocarcinoma (COAD), non‐small‐cell lung cancer (NSCLC), and head and neck squamous cell carcinoma (HNSCC)." (PMID 30665945, 2019). "Studies have shown that the epigenetic state is changed in bladder cancer cells with low KMT2C activity, and there is decreased expression of genes involved in DNA repair." (PMID 31590683, 2019). "Here, we show that downregulation of KMT2C in bladder cancer cells leads to extensive changes in the epigenetic status and the expression of DNA damage response and DNA repair genes." (PMID 30665945, 2019). "Downregulation of KMT2C in bladder cancer cells leads to DNA damage and genomic instability." (PMID 39021676, 2024). "One potential mechanism could be that the mutated segments cover specific bladder cancer-related pathogenic genes, such as TP73, KMT2C, and FOXA2, or affect some tumor suppressor genes." (PMID 39349436, 2024). "Therefore, PARP inhibitors have synthetic lethal effects in cancer cells with low KMT2C activity, especially in epithelial carcinoma, such as bladder cancer, colon cancer, NSCLC, and HNSCC." (PMID 31590683, 2019). "KMT2C was also demonstrated to participate in DDR, and bladder cancer cells having low KMT2C activity cannot efficiently repair the dsDNA breaks by homologous recombination." (PMID 33302406, 2020).
bladder cancer (continued). "Among the top ten genes, PIK3CA, RYR2, and KMT2C were highly expressed in the bladder cancer compared to normal bladder tissue (P < 0.001)." (PMID 33344221, 2020).
colorectal cancer (21 papers, 2011 to 2025). A primary or metastatic malignant neoplasm that affects the colon or rectum. "Mutations of KMT2C (MLL3) have been found in pancreatic cancer, gastric cancer, ovarian cancer, colorectal cancer, cholangiocarcinoma, bladder transitional cell carcinoma, etc.." (PMID 33726759, 2021). "Deletion of KMT2C has also been identified in colorectal cancer (CRC), and somatic mutations in KMT2C have been identified as potential drivers of tumorigenesis in several tumor types, including CRC." (PMID 32471474, 2020). "However, loss of function mutations in KMT2C, a histone lysine methyltransferase, have been identified in a number of cancers, and colorectal cancer cell lines, pointing towards a tumour suppressor role." (PMID 28288169, 2017). "Accordingly, KMT2C has been reported as a tumor repressor frequently altered in several types of cancers, including myeloid leukemia, colorectal cancer, medulloblastoma, pancreatic ductal adenocarcinoma, glioblastoma, and lung adenocarcinoma." (PMID 33655698, 2021). "Abnormalities in DNA methylation caused by germline mutations in the KMT2C gene were found in Chinese AML and colorectal cancer families and may be responsible for the pathogenesis of patients in the family lines." (PMID 39165358, 2024). "Results indicate that KMT2C inactivation may promote colorectal cancer development through transcriptional dysregulation in several pathways with known cancer relevance." (PMID 32471474, 2020). "Furthermore, the restoration of KMT2C expression reduced the growth of colorectal cancer (CRC) cells and reinforced the genome-wide H3K4me1 mark at the enhancers, which also suggests that inactivated KMT2C could promote CRC development through transcriptional dysregulation." (PMID 33302406, 2020). "The non-functional KMT2C/MLL3 promote colorectal cancer development by dysregulation in transcriptional pathways." (PMID 39390002, 2024).
medulloblastoma (21 papers, 2012 to 2026). A malignant, invasive embryonal neoplasm arising from the cerebellum. "In another study, researchers identified inactivating mutations in the histone lysine N -methyltransferase genes KMT2C or KMT2D in 16% of patients with childhood medulloblastoma (MB)." (PMID 39165358, 2024). "KMT2C was one of the first few recurrently mutated genes identified in a sequencing study of early medulloblastoma." (PMID 39165358, 2024). "In the previous investigation, the KMT2C gene was found to be linked with carcinogenesis progression of the lung, endometrial cancers, and medulloblastomas." (PMID 35409657, 2022). "KMT2C was among the first few recurrently mutated genes identified in early medulloblastoma sequencing studies." (PMID 33172502, 2020). "KMT2C mutations were present in 30% of adult medulloblastoma cases, distributed across all four molecular groups." (PMID 33172502, 2020). "In our adult medulloblastoma cohort, KMT2C was one of the most frequently mutated genes, with mutations detected in 30% of cases across ages, sexes, histological types and molecular groups, so it is a potential biomarker for stratifying adult medulloblastoma patients." (PMID 33172502, 2020). "Recurrent epigenetic alterations in SHH-activated medulloblastoma have been described in MLL2/KMT2D and MLL3/KMT2C, two lysine methyltransferases associated with an active chromatin state and the H3K4me2/3 status." (PMID 37568705, 2023). "Chromosome 7, with frequent copy number gains in all four cancers, harbors several key oncogenes such as EGFR, CDK6, and MET in glioma; KMT2C and PMS2 in medulloblastoma; BRAF, RAC1, and TRRAP in melanoma." (PMID 41537310, 2026). "DNA alterations in KMT2C and MUC4 have been observed in the somatic tissue of medulloblastoma and head and neck squamous cell carcinoma patients, respectively." (PMID 32508881, 2020). "The original medulloblastoma exome sequencing led to the discovery of frequent mutations in the histone lysine methyltransferase gene KMT2D/MLL2 and its homolog KMT2C/MLL3, which were not previously linked to cancer." (PMID 24240169, 2013).
Kleefstra syndrome (17 papers, 2014 to 2025). A genetic disorder characterized by intellectual disability, childhood hypotonia, severe expressive speech delay and a distinctive facial appearance with a spectrum of additional clinical features. "This included genes like KMT2C, involved in Kleefstra syndrome (OMIM #617768), and GRIN2A of which heterozygous mutations cause epilepsy and speech delay (OMIM #245570)." (PMID 34663447, 2021). "Mutations of KMT2C have been found in neurodevelopmental disorders, such as Kleefstra syndrome, intellectual disability, and autism spectrum disorders." (PMID 34945726, 2021). "Mutations in the Kmt2c gene have been reported in neurodevelopmental disorders, including ASD, Kleefstra syndrome, and intellectual disability." (PMID 36803626, 2023). "The remaining three genes KMT2C, RELN, and BRCA2, had been previously associated with Kleefstra syndrome (OMIM #617768), Familial Temporal Lobe Epilepsy (OMIM #616436), and with different types of cancer, respectively." (PMID 36568968, 2022). "In addition, pathogenic de novo variants in MBD5 and in other epigenetic regulators (SMARCB1, NR1I3, KMT2C) were reported in individuals with a clinical diagnosis of Kleefstra syndrome (KS; OMIM #610253)." (PMID 35205380, 2022). "In addition to EHMT1 mutations, de novo variants were reported in four additional genes (MBD5, SMARCB1, NR1I3, and KMT2C), in single individuals with clinical characteristics overlapping Kleefstra syndrome." (PMID 29069077, 2017). "Kleefstra syndrome (KLEFS, OMIM #610253, #617768) is a rare condition characterized by heterozygous genomic deletions at chromosome 9q34.3 removing the EHMT1 gene or EHMT1 point mutations (KLEFS1), or pathogenic variants in KMT2C on chromosome 7q36.1 (KLEFS2), mostly de novo." (PMID 33959609, 2021). "In Drosophila, we demonstrate molecular convergence between trr, the KMT2C/D ortholog, and G9a, the ortholog of EHMT1, which is involved in Kleefstra syndrome." (PMID 29069077, 2017). "While congenital cataract is reported in 1–2% of children with T21 and has not been reported as being part of Kleefstra syndrome, an RNA-seq study of the developing lens identified KMT2C as a candidate for cataract, based on enrichment in the developing lens." (PMID 36672956, 2023).
pancreatic cancer (14 papers, 2012 to 2024). "In the present review, we summarized the mutations of epigenetic regulators, including ARID1A, SMARCA2, SMARCA4, KDM6A, KMT2C, KMT2D, and BRD4 in GI cancers—in particular, pancreatic cancer—and found these regulators to be frequently mutated." (PMID 31238554, 2019).
gastric cancer (12 papers, 2015 to 2025). A primary or metastatic malignant neoplasm involving the stomach. "KMT2C, a frequently mutated driver gene, has been reported in the literature to have an impact on gastric cancer progression." (PMID 37737478, 2023). "A previous genomics study showed that 47% of gastric cancer patients had mutations in KMT2C or KMT2D." (PMID 33726759, 2021). "Analysis of clinical samples has revealed reduced KMT2C expression in larynx carcinoma, pancreatic ductal adenocarcinoma, and gastric cancer, and silencing of KMT2C due to promoter DNA hypermethylation has been observed in urothelial cancer." (PMID 32471474, 2020). "The group with SOX2 suppression had higher rates of mutations in many gastric cancer-associated genes such as epigenetic modifiers ARID1A, KMT2D, KMT2C, and KMT2B, as well as higher rates of mutations in genes encoding for receptor tyrosine kinases ERBB4 and FGFR1." (PMID 40149431, 2025). "However, SOX2 suppression may be permissive for a sub-set of gastric cancers with CDX2 induction to acquire mutations in epigenetic modifier genes, including ARID1A, KMT2D, KMT2C, KMT2A, and KMT2B." (PMID 40149431, 2025). "The analysis of the PRISM data also identified the interaction between the driver gene KMT2C and the drug Capecitabine, an oral prodrug of 5-fluorouracil that targets TYMS and is commonly used in the treatment of advanced gastric cancer 48,49." (PMID 37737478, 2023).
prostate carcinoma (11 papers, 2013 to 2024). A carcinoma that arises from epithelial cells of the prostate gland. "Here, they used data from the International Cancer Genome Consortium (ICGC) and found that KMT2C truncating mutations were associated with reduced disease-free survival in prostate cancer." (PMID 37415738, 2023). "PTEN-deficient prostate cancer patients often also harbor inactivating mutations in lysine N-methyltransferase 2C (KMT2C) and mice bearing both alterations develop prostate cancer metastases with a hallmark c-Myc gene signature." (PMID 36768610, 2023). "Loss of PTEN and KMT2C in prostate cancer results in loss of senescence, metastatic dissemination and reduced life expectancy." (PMID 35354467, 2022). "Meanwhile, although KMT2C dysregulation plays an oncogenic role and is also a top mutated gene in prostate cancer (7%), the clinical significance of KMT2C mutations in prostate cancer is currently understudied." (PMID 37415738, 2023). "Mechanistically, we observed that KMT2A and KMT2C differentially regulate the H3K4me1 and H3K4me2 in prostate cancer." (PMID 37345101, 2023).
colon cancer (10 papers, 2011 to 2024). "KMT2C, a histone methyltransferase involved in transcriptional co-activation and co-repression, is seen as a silent/intronic mutation or structural alteration in hepatic metastases from breast, melanoma, and colon cancer." (PMID 39165358, 2024). "In particular, histone-lysine N-methyltransferase genes KMT2D, KMT2C and KMT2B in bladder, lung and endometrial cancers, whereas the KMT2A is mostly mutated in non-small cell lung cancer and colon cancer." (PMID 34302033, 2021). "In addition, chromosome fragmentation leading to rearrangement of KMT2C has been reported in colon cancer." (PMID 39165358, 2024).
glioblastoma (9 papers, 2014 to 2025). The most malignant astrocytic tumor (WHO grade IV). "They found that the KMT2C gene was among the top 20 glioblastoma-mutated genes among other missense-mutated genes." (PMID 40564017, 2025). "In a recent study, the KMT2C gene was identified as mutated and was associated with cancer stem cells in four glioblastoma patients using comparative analysis and the exome sequencing." (PMID 40564017, 2025). "According to the Catalogue Of Somatic Mutations In Cancer (COSMIC), the KMT2C gene is mutated in 4% of glioblastomas." (PMID 40564017, 2025). "Their findings showed that the KMT2C gene was one of the epigenetic modifier genes with mutations and frequent copy number alterations (11%) in lower-grade gliomas and a rare mutation frequency in primary glioblastoma (5%)." (PMID 40564017, 2025). "To address the essential role of ASH2L for glioblastoma cell survival further, we focused our attention to chromatin modifying complexes, specifically, SET1/MLL family of histone methyltransferases SET1 (SETD1A), SET1B (SETD1B), MLL1 (KMT2A), MLL2 (KMT2B), MLL3 (KMT2C) and MLL4 (KMT2D)." (PMID 37974198, 2023).
Intellectual disability (9 papers, 2017 to 2023). "KLEFS-2 (OMIM 617768) is a rare genetic disorder associated with mutations in the KMT2C gene, characterized by individuals exhibiting intellectual disability, childhood hypotonia, autistic-like features, and distinctive facial features." (PMID 38090150, 2023). "Human with mutations in KMT2C have shown to have mild to severe intellectual disability, phenotype also associated to ASD." (PMID 37538398, 2023). "While KMT5A represents a novel gene, KMT2C, also known as MLL3, is a well-established gene linked to intellectual disability and autism." (PMID 38025430, 2023). "The absence of intellectual disability is also observed in other genes (for example, SCAF1, HNRNPUL2, GIGYF1, KDM5B and KMT2C) with substantial contribution from rare inherited variants and modest effect size." (PMID 35982159, 2022).